FMR1 (fragile X messenger ribonucleoprotein 1)
Diseases named in the same sentence as FMR1 in open-access papers (continued):
Sharing a sentence is not in itself a finding about the gene and the disease.
fragile X syndrome (continued). "Mutations in the untranslated region (UTR) of genes are extremely rare causes of Mendelian diseases and even the few described (e.g. FMR1-related fragile-X syndrome, DMPK-related myotonic dystrophy) tend to represent repeat expansion." (PMID 28754144, 2017). "Fragile-X syndrome (FXS) is another inherited disorder where fragile X mental retardation 1 (FMR1) gene silencing leads to mental retardation and autism in males." (PMID 28538662, 2017). "Using the Fmr1 null mouse model of fragile X syndrome, we have identified brain regions, gene networks, and molecular pathways responsive to a social stimulus." (PMID 28649315, 2017). "Mutations in its gene result in the most common form of inherited human mental retardation linked to autistic symptoms (fragile X syndrome, FXS), and respective knockout (Fmr1 KO) mice provide excellent animal model to approach the human condition." (PMID 26319558, 2016). "We will specifically address two genetic intellectual disabilities, Down Syndrome (DS), caused by trisomy 21, and Fragile X Syndrome (FXS), caused by the absence of FMRP protein upon a “CGG” triplet expansion at the 5′-UTR of the FMR1 gene." (PMID 27547454, 2016). "This was achieved using a microfluidic brain interface and open-dura surgery, with the goal of abolishing neuronal Ca2+ signaling in the visual cortex of wild-type mice and rodent models of fragile X syndrome (Fmr1 knockout [KO])." (PMID 27221801, 2016). "Fragile X syndrome (FXS) is the most common form of inherited mental retardation, and is caused by a mutation in the fragile X mental retardation gene (Fmr1)." (PMID 27517961, 2016). "Clinical features such as psychiatric problems like depression and anxiety, family history of Fragile X syndrome, and genetic evaluation of FMR1 premutation are important for the differential diagnosis of NIID and FXTAS." (PMID 27797808, 2016). "The mutation responsible for FXS is a large expansion of the CGG repeats in the promoter region of the FMR1 gene resulting in the transcriptional silencing of the gene in the pathophysiology of Fragile X syndrome was hypothesized." (PMID 26712713, 2016). "Fragile X syndrome (FXS) is an X-linked genetic condition associated with an expansion of the trinucleotide CGG repeat within the 5’ untranslated region of the fragile X mental retardation 1 (FMR1) gene." (PMID 26855682, 2016). "Since the original generation of the Fmr1 knock-out mouse model of fragile X syndrome in 1994, hundreds of publications have evaluated the behavioral phenotypes of Fmr1 mice, on both B6 and FVB genetic backgrounds." (PMID 27022628, 2016). "Our data also describe for the first time broad changes in FMR1 5hmC levels and distribution in FXS PBMCs, highlighting novel molecular features that may be associated with FMR1 epigenetic regulation in fragile X syndrome patient cells." (PMID 26855684, 2016). "A similar approach has also been used in the Fmr1-KO mice and significant long-term beneficial effects on the pathological fragile X syndrome (FXS) phenotype have been detected." (PMID 27274875, 2016). "Traditional cognitive tests have revealed surprisingly normal performance in the Fmr1 knock-out mouse model (Fmr1) of fragile X syndrome (FXS)." (PMID 27022628, 2016). "We describe a 38 year old male carrying a 100% methylated FM detected with Southern blot (SB), which is consistent with complete silencing of FMR1 and a diagnosis of fragile X syndrome." (PMID 27657133, 2016). "We have previously shown that in the mouse model of fragile X syndrome—Fmr1 KO mice—there is an increased synaptic translation of MMP-9, which results in the higher activity of the enzyme on synapses and contributes to dendritic spine dysmorphologies." (PMID 26319558, 2016).
fragile X syndrome (continued). "Large expansions of CGG repeats (> 200 repeats) in the FMR1 gene, referred to as full mutations, cause DNA methylation and transcriptional silencing, resulting in fragile X syndrome (FXS), a neurodevelopmental disorder characterized by intellectual disability and autism." (PMID 28005950, 2016). "This pattern bears an interesting resemblance to the excess of urinary inosine and hypoxanthine detected in Fmr1 knock-out mice, an animal model of fragile-X syndrome." (PMID 27904735, 2016). "After successful excision of the full mutation, we found one in five derived clonal lines had both transcriptional and translational reactivation, suggesting a successful approach for reactivation of FMR1 in fragile X syndrome." (PMID 27768763, 2016). "Methylation of the fragile X mental retardation 1 (FMR1) exon 1/intron 1boundary positioned fragile X related epigenetic element 2 (FREE2), reveals skewedX-chromosome inactivation (XCI) in fragile X syndrome full mutation (FM: CGG > 200)females." (PMID 26132880, 2015). "Given the importance of spine morphology on synaptic physiology, the increased density and elongation of spines in the fmr1-/y accumbens is likely to contribute to the disrupted synaptic plasticity in the mouse model of Fragile X syndrome." (PMID 25859182, 2015). "In line with the “mGluR” theory of Fragile X Syndrome, pharmacological blockade or reduced expression of group I mGlu receptors were found to rescue cognitive impairment and abnormal behavior in Fmr1 KO mice." (PMID 25814945, 2015). "Other potential genetic causes of this phenotype, Prader-Willi syndrome and Fragile X syndrome, had previously been excluded in the proband by SNRPN DNA methylation analysis and demonstration of normal 5’-UTR CGG repeat number in the FMR1 gene." (PMID 26120850, 2015). "CGG repeat expansions in the Fragile X mental retardation 1 (FMR1) gene are responsible for a family of associated disorders characterized by either intellectual disability and autism Fragile X Syndrome (FXS), or adult-onset neurodegeneration Fragile X-associated Tremor/Ataxia Syndrome." (PMID 26322075, 2015). "Fragile X Syndrome, FXTAS, and FXPOI are X-linked disorders that arise from expansions in a CGG-repeat region in the 5′-UTR of the FMR1 gene." (PMID 26322075, 2015). "Fragile X syndrome is caused by silencing of the FMR1 gene and the subsequent loss of fragile X mental retardation protein (FMRP, also known as FXR1P)." (PMID 26097465, 2015). "PAK inhibitors have also been shown to rescue fragile X syndrome phenotypes in Fmr1 KO mice, suggesting an important role for Pak serine/threonine-protein kinase activity in ASD and ID." (PMID 25816101, 2015). "Here we show that LP-211, a high affinity selective agonist of 5-HT7 receptors, reverses mGluR-LTD in wt and Fmr1 KO mice, correcting a synaptic malfunction in the mouse model of Fragile X Syndrome." (PMID 25814945, 2015). "Using a quantitative mass spectrometry-based approach we analyzed the lipid raft proteome of Fmr1 knockout mice, an animal model of Fragile X syndrome, and identified candidate proteins that are differentially represented in Fmr1 knockout mice lipid rafts." (PMID 25849048, 2015). "In the Fmr1 KO mouse model of fragile X syndrome, similar to our findings, it was shown broader AI tuning curves with higher latency variability and an over-representation of high frequencies between 11–25 kHz." (PMID 26635548, 2015). "Our findings provide insight to aid identification of molecular and cellular dysfunctions arising from Fmr1 silencing and for uncovering shared pathologies between Fragile X syndrome and other autism spectrum disorders." (PMID 25849048, 2015). "It was previously shown that the fmr1 knock-out mice, a common mouse model of Fragile X Syndrome, recapitulates this motor learning deficit and that the deficit is associated with altered plasticity of dendritic spines." (PMID 25950728, 2015).
fragile X syndrome (continued). "For example, miR-130b has been shown to regulate Fmr1 expression, which is lost in the disorder fragile X syndrome." (PMID 26635721, 2015). "For example, the Fmr1 KO mouse model of Fragile X Syndrome exhibit an abnormally enhanced mGluR-LTD and show autistic features and reduced behavioral flexibility." (PMID 25221471, 2014). "In order to address this question, we investigated retinal features in a murine model of MD with autistic features, the Fmr1 KO mice, model of Fragile X Syndrome." (PMID 25153086, 2014). "Expansion of repetitions of the trinucleotide sequence of cytosine and guanine (CGG) on the FMR1 gene is the cause of several well-described disorders including fragile X syndrome (FXS), fragile X tremor ataxia syndrome (FXTAS), and fragile X primary ovarian insufficiency (FXPOI)." (PMID 25250044, 2014). "Fragile X syndrome occurs as a result of a trinucleotide (CGG) repeat expansion in the 5′ untranslated region of the fragile X mental retardation (FMR1) gene." (PMID 24839550, 2014). "Expansion of a (CGG)n sequence in the 5'-UTR of the FMR1 gene to >200–2000 repeats abolishes its transcription and initiates fragile X syndrome." (PMID 25268620, 2014). "In a mouse model of fragile X syndrome (Fmr1-knockout mice), BDNF levels are decreased in the cortex but increased in the hippocampus." (PMID 25182223, 2014). "We observed significantly impaired responses to speech, noise bursts, and tones in AAF, primary auditory cortex, and ventral auditory field in the Fmr1 KO rat model of fragile X syndrome." (PMID 25140133, 2014). "In contrast to Fragile X syndrome, in which the FMR1 gene harbors over 200 CGG repeats but is transcriptionally silent, the clinical features of FXTAS arise from a toxic gain of function of the elevated levels of FMR1 transcript containing the long CGG tract." (PMID 25161746, 2014). "Many IVF programs currently test oocyte donor's FMR1 status to prevent transmission of maternal premutation range (CGGn∼55–200) and/or expansions to full mutations (CGGn>200; fragile X syndrome; FXS) and other associated neuro-psychiatric complications, mostly affecting males." (PMID 25019151, 2014). "Classical eye blink conditioning deficit has also been found in global and Purkinje cell-specific Fmr1 gene knockout mice which show morphological and behavioral features similar to fragile X syndrome patients." (PMID 26331028, 2014). "Minocycline, a drug whose pleiotropic effects include the inhibition of MMP-9 activity, reverses filopodia transformation toward mature spines in an animal model of fragile X syndrome (Fmr1 knockout mice)." (PMID 25071472, 2014). "Triplet repeat expansions in the 5′ untranslated region of the fragile X gene (FMR1) are pathogenic and result in a spectrum of phenotypes, the most well characterized of which is fragile X syndrome (FXS; OMIM #300624, Online Mendelian Inheritance in Man, 2013a)." (PMID 25120560, 2014). "The CYFIP1 gene encodes a protein that interacts with FMRP, the protein product of the FMR1 gene responsible for fragile X syndrome." (PMID 24778887, 2014). "Long and thin immature dendritic spines are also observed in Fmr1 knockout mice, a model of fragile X syndrome." (PMID 25071472, 2014). "The fact that the Fmr1 transcripts studied here are apparently translated has definite implications with regard to our view of the biology of human Fragile X Syndrome." (PMID 23505481, 2013). "The RhoA pathway appears to be intact in the Fmr1 KO Fragile X syndrome model mouse but we have obtained evidence that TBS fails to engage other GTPases and downstream elements involved in the stabilization of cytoskeletal changes in these mice." (PMID 23966908, 2013).
fragile X syndrome (continued). "The Fmr1 KO model of Fragile X syndrome presented an interesting condition in which actin filaments formed after TBS but did not properly stabilize." (PMID 23966908, 2013). "We show that it is possible to reactivate FMR1 transcription in fibroblasts of fragile X syndrome patients by treatment with methotrexate." (PMID 24020679, 2013). "Wnt2 expression is reduced in the hippocampus and cortex of FMR1 knockout mice, a mouse model for Fragile-X syndrome." (PMID 23639831, 2013). "While their genetic determinants are different (TSC1/TSC2 for tuberous sclerosis and FMR1 for fragile X syndrome), their gene products both regulate protein synthesis in neurons." (PMID 23935565, 2013). "This deletion resulted in hemizygosity for 113 RefSeq genes including the FMR1 and iduronate 2-sulfatase (IDS) genes which are associated with Fragile X syndrome (FXS) and Hunter syndrome, respectively." (PMID 23634718, 2013). "LP-211 has been proposed as a tool for rescuing the fragile X syndrome phenotype in the Fmr1 (fragile X mental retardation 1) knockout mice model." (PMID 25505568, 2013). "Fragile X syndrome is a form of inherited mental retardation in humans that results from expansion of a CGG repeat in the Fmr1 gene." (PMID 23300470, 2012). "Fragile X syndrome (FXS) is a well-recognized form of inherited mental retardation, caused by a mutation in the fragile X mental retardation 1 (Fmr1) gene." (PMID 22984567, 2012). "In this study, we used cultured cerebellar granule cells (CGCs) from Fmr1 knockout (KO) mice, a mouse model for fragile X syndrome (FXS) and syndromic autism, to examine the effects of memantine on dendritic spine development and synapse formation." (PMID 22615862, 2012). "Fragile X syndrome is a form of inherited mental retardation in humans that results from expansion of a CGG repeat in the Fmr1 gene on the X chromosome." (PMID 23300470, 2012). "Fragile X syndrome (FXS) is a form of inherited mental retardation in humans that results from expansion of a CGG repeat in the Fmr1 gene." (PMID 23300470, 2012). "Furthermore, many links between miRNA pathways and FMR1, the gene mutated in fragile X syndrome (FXS), were discovered." (PMID 21342132, 2011). "MPEP is effective in treating autism-related symptoms in the Fmr1 mouse model of Fragile X syndrome, and fluoxetine is under evaluation to treat repetitive behavior and anxiety in autistic patients and is currently used to treat depression." (PMID 21826280, 2011). "A Prader-Willi syndrome-like phenotype with obesity has been described in fragile X syndrome individuals with the CGG expansion mutation, indicating that the obesity is probably due to loss of FMR1 function and interaction with other genes." (PMID 22043167, 2011). "The Fmr1-KO mouse is an example of this approach, modeling Fragile X syndrome, a well-known genetic disorder presenting ASD symptoms." (PMID 21364941, 2011). "Modeling the human behavior deficits seen in Fragile X Syndrome in mouse models has proven challenging, although some marked differences between Fmr1 null mice and normal littermates have been characterized." (PMID 20011099, 2009). "These mice phenocopy the symptoms of Fragile X Syndrome in the existing Fmr1–null mouse, as assessed by testicular size, behavioral phenotyping, and electrophysiological assays of synaptic plasticity." (PMID 20011099, 2009). "Fragile X Syndrome (FXS), a common genetic cause of autism and mental retardation, is usually caused by transcriptional silencing of the FMR1 gene." (PMID 20011099, 2009). "The most widely used model for Fragile X Syndrome, the Fmr1tm1Cgr mouse, is a complete null due to the insertion of the neo cassette in exon 5 of the Fmr1 gene." (PMID 20011099, 2009). "In most patients with Fragile X syndrome, the FMR1 gene is transcriptionally silenced when the CGG triplet repeat in the 5′-untranslated region (UTR) is methylated upon expansion to greater than 200 copies." (PMID 19888420, 2009).
fragile X syndrome (continued). "Fragile X syndrome, caused by a large expansion of a CGG trinucleotide repeat within the FMR1 gene located on chromosome X (q27.3), is considered the most common cause of inherited mental retardation." (PMID 19822023, 2009). "Inactivation of the human FMR1 ortholog leads to Fragile-X syndrome, which is the most common form of inherited mental retardation and is associated with severe neurodevelopmental and behavioral abnormalities." (PMID 19032789, 2008). "In the present manuscript, we report the discovery and functional characterization of a primate-specific noncoding RNA (FMR4) that becomes silenced as a result of the CGG expansion in the 5′ UTR of FMR1 in fragile X syndrome." (PMID 18213394, 2008). "We describe the coexistence in a large Italian kindred of Fragile X syndrome and familial POF in females with ovarian dysfunctions who carried normal or expanded FMR1 alleles." (PMID 17428316, 2007). "The Fragile-X syndrome should be excluded by DNA-analysis of the FMR1 gene (molecular investigation the expansion of the CGG repeat in the FMR1 gene)." (PMID 16831221, 2006). "The Fmr1 KO mouse is a valid model of the Fragile X Syndrome and many data on behavioral and sensory-motor characteristics of this model have been gathered." (PMID 16998604, 2006). "Our patient also had a diagnosis of fragile X syndrome, a genetic disorder characterized by a deficiency or absence of the fragile X mental retardation 1 protein (FMR1)." (PMID 40062023, 2025). "Fragile X Syndrome (FXS), the most common genetic cause of intellectual disability and autism spectrum disorder (ASD), results from silencing of the FMR1 gene and consequent loss of Fragile X Messenger Ribonucleoprotein (FMRP)." (PMID 41324081, 2025). "Fragile X syndrome (FXS) is a genetic disorder of the development primarily caused by mutation of the Fmr1 gene that leads to its inactivation and the loss of fragile X Messenger Ribonucleoprotein (FMRP)." (PMID 40282228, 2025). "In Fragile X syndrome (FXS; MIM 300624), a leading cause of ID, ASO-mediated targeting of intron retention in FMR1 transcripts effectively corrects abnormal alternative splicing and rescues FMRP expression in patient-derived cells." (PMID 41244709, 2025). "Moreover, in fragile X syndrome (FXS) model mice (Fmr1 knockout), cultured NPCs exhibited tPA overexpression in glial cells, which contributed to aberrant neuronal migration." (PMID 41515965, 2025). "Likewise, mitral cells in the Fmr1 knock-out (KO) model of fragile X syndrome exhibit unstable membrane potentials and increased response variability following electrical stimulation of the glomeruli." (PMID 41062277, 2025). "Fragile X Syndrome is a genetic form of intellectual disability affecting 1/4000 males and 1/8000 females, caused by the silencing of the FMR1 gene, located on the X chromosome, coding for Fragile X Messenger Ribonucleoprotein Protein (FMRP)." (PMID 40141138, 2025). "Fragile X syndrome: Parkinsonism has been reported in fragile X-associated tremor/ataxia syndrome (FXTAS), a late-onset neurodegenerative disorder associated with premutation alleles (55–200 CGG repeats) of the fragile X mental retardation 1 (FMR1) gene." (PMID 40243562, 2025). "Notably, FMR1 and HNRNPH2 are two known splicing factors associated with fragile X syndrome and X-linked development disorders, they exhibited significant female-biased expression." (PMID 40866999, 2025). "Fragile X syndrome (FXS), the most common genetic cause of ASD, is associated with intellectual disability and results from a recessive X-linked mutation in the fragile X messenger ribonucleoprotein 1 (FMR1) gene." (PMID 39997759, 2025). "At the molecular level, FXTAS is caused by a toxic gain-of-function mechanism associated with elevated FMR1 mRNA levels, leading to RNA toxicity rather than FMRP deficiency, which underlies fragile X syndrome." (PMID 40362640, 2025).